MMP12 (matrix metallopeptidase 12)
Diseases named in the same sentence as MMP12 in open-access papers (continued):
Sharing a sentence is not in itself a finding about the gene and the disease.
oral diseases (2 papers, 2023 to 2025). "MMPs (particularly MMP12) can be regarded as risk factors for oral diseases, and their levels can be valuable symbols for early diagnosis and assessment of prognosis." (PMID 36902078, 2023). "Therefore, more future study is required to elucidate these pathways and aid in developing MMP12-based diagnostic and therapeutic techniques for oral disorders." (PMID 36902078, 2023). "All in all, MMP12 may be considered a potential diagnostic and therapeutic target for various oral diseases." (PMID 36902078, 2023). "The potential role of MMP12 in oral diseases still needs to be elucidated, and more clinical trials need to find the proper combination of MMP12 inhibitors or their activators." (PMID 36902078, 2023). "MMP12 is considered a key protein and has critical roles in the physiological and pathological activities of various oral diseases." (PMID 36902078, 2023). "MMP-12 is likely used as a biomarker for various oral diseases." (PMID 39102860, 2025). "Although there may be a potential role of MMP12 in oral diseases, the exact pathophysiological role of MMP12 remains to be elucidated." (PMID 36902078, 2023). "Furthermore, MMP12 has been explored as the molecular target for the diagnosis and treatment of oral diseases." (PMID 36902078, 2023). "Given the implication of MMP12 in various oral diseases, it will, therefore, be of great interest to see whether disease progression in relevant animal models can be prevented with these specific MMP12 inhibitors." (PMID 36902078, 2023). "Understanding the cellular and molecular biology of MMP12 is essential, as MMP12 could be a potential target for developing therapeutic strategies targeting inflammatory and immunologically related oral diseases." (PMID 36902078, 2023). "The mechanisms of MMP12 in oral disorders are largely unknown." (PMID 36902078, 2023). "Therefore, MMP12 might serve as an important molecular target for the diagnosis and treatment of oral diseases." (PMID 36902078, 2023).
pancreatic adenocarcinoma (2 papers, 2019 to 2020). "MMP12 was significantly downregulated in pancreatic adenocarcinoma, but significantly upregulated in stomach adenocarcinoma (P < 0.05), suggesting that the role of MMP12 in the progression of cancer differed among different types of cancers." (PMID 31119098, 2019). "We analyzed mRNA expression levels of LIFR, PIK3R1 and MMP12 in cholangio carcinoma, liver hepatocellular carcinoma, pancreatic adenocarcinoma, and stomach adenocarcinoma, with the data from the TCGA." (PMID 31119098, 2019).
renal fibrosis (2 papers, 2017 to 2025). A final common manifestation of a wide variety of chronic kidney diseases characterized by glomerulosclerosis and tubulointerstitial fibrosis. "Among these, only Mmp12 was highly expressed in the Ccl6+Ccr2+Arg1+ population, suggesting that these macrophages may contribute to the progression of renal fibrosis through tissue remodeling mechanisms." (PMID 40953007, 2025). "The COL4A3−/−/ITGA2−/− double knockout Alport mouse model has delayed renal fibrosis compared with COL4A3−/−/ITGA2+/+ Alport mice, which express significantly higher levels of MMP2, MMP9, MMP12, and TIMP155." (PMID 29196624, 2017). "Furthermore, M2 macrophages promote renal fibrosis by secreting pro-fibrotic factors such as TGFβ, matrix metalloproteinases (MMP-2, MMP-9, MMP-12), galectin-3, and platelet-derived growth factors, which activate fibroblasts and drive extracellular matrix accumulation." (PMID 40953007, 2025).
steatosis (2 papers, 2015 to 2021). Increased lipid within the cytoplasm of cells. "We found that Mmp12 (P < 0.001) and Mmp13 (P < 0.05) were significantly upregulated in the liver of mice with steatosis compared to normal livers using 2-way ANOVA followed by the Bonferroni post-test." (PMID 25880591, 2015).
trachoma (2 papers, 2017 to 2020). "In another murine corneal injury model, MMP12 was found to enhance early wound repair through increasing neutrophil infiltration and epithelial cell migration, suggesting that overexpression in trachoma might contribute to leukocyte infiltration." (PMID 31964744, 2020).
vitamin D deficiency (2 papers, 2015 to 2022). A nutritional condition produced by a deficiency of VITAMIN D in the diet, insufficient production of vitamin D in the skin, inadequate absorption of vitamin D from the diet, or abnormal conversion of vitamin D to its bioactive metabolites. "Vitamin D deficiency was also associated with an increased production of matrix metalloproteinase-12 (MMP-12), indicative of increased proteolysis in the lungs." (PMID 35236342, 2022).
adenocarcinoma of the colon (1 paper, 2016). "Differences in the expression pattern of MMP7, MMP10 and MMP12 in 78 serum specimens of patients with an adenocarcinoma of the colon and serum specimens of a healthy control group were assessed using Luminex-100 technologies." (PMID 27431388, 2016).
airway hyperresponsiveness (1 paper, 2021). "When mice subjected to allergic airway inflammation via exposure to the house dust mite antigen (HDM) were infected with RSV (HDM/RSV), MMP-12 expression, viral load, neutrophil infiltration, and airway hyperresponsiveness (AHR) were increased compared to those in the HDM and RSV groups." (PMID 34703996, 2021).
Airway obstruction (1 paper, 2025). Obstruction of conducting airways of the lung. "This highlights the need to further explore the role of MMP-12 in allergen-induced bronchial fibrosis and airway obstruction." (PMID 40940719, 2025). "Indeed, in the current study, mice challenged with Aspergillus and treated with two different MMP-12 inhibitors (PF-00356231HCL and MMP408) showed improved bronchial fibrosis and airway obstruction." (PMID 40940719, 2025).
allergic disease (1 paper, 2022). An immune response that occurs following re-exposure to an innocuous antigen, and that requires the presence of existing antibodies against that antigen. "Similarly, MMP12, a proinflammatory factor mainly produced by macrophages, is demonstrated to be involved in the development of allergic diseases." (PMID 35733520, 2022).
atopic dermatitis (1 paper, 2024). "We also investigated the regulatory effects of dhAvD on CCL20 and IL-23, keratinocyte-derived factors that enhance Th2 cytokines that are highly expressed in atopic dermatitis, and their downstream molecules, MMP-9 and MMP-12." (PMID 39329899, 2024).
Basement membrane disease (1 paper, 2016). "Similar results were observed in a study of antiglomerular basement membrane disease in rats in which administration of an antibody against MMP-12 reduced glomerular macrophage accumulation, preserved glomerular structure, and protected against renal dysfunction." (PMID 26822129, 2016).
Bcc (1 paper, 2024). "Besides, patients with Bcc tended to show an increase in sputum MMP-9 and reduction in MMP-12 concentrations." (PMID 39011515, 2024).
benign prostatic hyperplasia (1 paper, 2024). A non-cancerous nodular enlargement of the prostate gland. "In our preliminary clinical observation, we found that MMP-12 was highly expressed in CRPC but was hardly expressed in patients with benign prostatic hyperplasia (BPH) and that high expression of MMP-12 was associated with poor pathological stage." (PMID 38511770, 2024).
bladder tumor (1 paper, 2024). "It is noteworthy that clinical studies have demonstrated an association between the polymorphism of the MMP12 G allele and an elevated risk of bladder tumor invasion and metastasis, attributed to the upregulation of MMP12 expression." (PMID 39557851, 2024).
Cachexia (1 paper, 2021). Severe weight loss, wasting of muscle, loss of appetite, and general debility related to a chronic disease. "One question is that if knockout MMP12 would reverse muscle loss under condition of cachexia." (PMID 34863141, 2021).
cardiomyopathy (1 paper, 2021). A disease of the heart muscle or myocardium proper. "Several of the proteins impacted by myectomy (POSTN, MMP12, CDON, NAMPT, HAMP, LTA4H) were previously reported to be altered in cardiovascular disease, cardiomyopathy, or vascular disease with effects mediated through inflammatory mechanisms." (PMID 33804404, 2021).
carpal tunnel syndrome (1 paper, 2020). Entrapment of the median nerve in the wrist that is characterized by numbness, tingling and painful movement. "DNA variants located within MMP1 (rs1799750), MMP3 (rs3025058, rs679620, rs591058, rs650108), MMP10 (rs486055), and MMP12 (rs2276109), have independently and/or in combination been associated with Achilles tendinopathy (AT) risk, Carpal Tunnel Syndrome (CTS) and ACL ruptures." (PMID 32650441, 2020).
cataract (1 paper, 2009). Partial or complete opacity of the crystalline lens of one or both eyes that decreases visual acuity and eventually results in blindness. "On the other hand, genes which are highly up-regulated in Dbl-lenses, such as Mmp12, Ccl2, and Spp1, have not been described in EMT occurring in these cataracts." (PMID 19759912, 2009).
cerebral infarct (1 paper, 2012). "Several matrix-methaloproteinases such as MMP2, MMP7, MMP9 and MMP12, were up-regulated after cerebral infarct." (PMID 23284893, 2012). "Many methalloproteinases showed highly altered expression, including MMP2 and MMP7 at 3 d after cerebral infarct, as well as MMP9 and MMP12 in the acute (24 h) phase." (PMID 23284893, 2012).
cervical dysplasias (1 paper, 2005). "MMP12 expression in cervical dysplasias and carcinomas has not been previously reported." (PMID 15989693, 2005).
cervical tumors (1 paper, 2021). "Analyses of IHC staining (P < 0.01), TCGA database (P < 0.01), and GEPIA database (P < 0.05) revealed that MMP12 was highly expressed in cervical tumors compared with normal tissues." (PMID 33958583, 2021). "Interestingly, MMP12 expression was significantly correlated with MTA2 expression in cervical tumors (P = 0.001)." (PMID 33958583, 2021). "Moreover, MMP12 expression in cervical tumors was strongly correlated with the decrease in overall survival rate (P = 0.036)." (PMID 33958583, 2021). "Subsequently, we analyzed MMP12 expression in cervical tumors." (PMID 33958583, 2021).
Chagas disease (1 paper, 2020). A parasitic infection caused by Trypanosoma cruzi. "Because myocardial expression of Mmp12 and Mmp13 that are encoded by macrophages was maximally increased, we also performed co-localization studies to examine whether macrophages contribute to profibrotic response in Chagas disease." (PMID 32098116, 2020).
cholangiocarcinoma (1 paper, 2020). A carcinoma that arises from the intrahepatic biliary tree (intrahepatic cholangiocarcinoma) or from the junction, or adjacent to the junction, of the right and left hepatic ducts (hilar cholangiocarcinoma). "In contrast, mononuclear phagocytes exhibited up‐regulation of chemokines such as CCL4, CCL4L2, and CCL3L3 in the cholangiocarcinoma samples and extracellular remodeling genes such as MMP19, MMP12, and HS3ST2 in the metastatic patients." (PMID 33332768, 2020).
cholesteatoma (1 paper, 2012). A pathologic process characterized by the proliferation of keratinizing squamous epithelium resulting in the accumulation of keratin and cells in the middle ear and/or mastoid. "Among the 811 up-regulated extramatrix protein genes, MMP1, MMP7, MMp9, MMP10 and MMP12 and their substrate Osteopontin (SPP1) were amplified and their expression was significantly higher in cholesteatoma than in external canal skin (logFC>10)." (PMID 23285167, 2012). "In cholesteatoma matrix metalloproteinases MMP1, MMP9, MMP10, and MMP12 were up-regulated." (PMID 23285167, 2012). "Real-time PCR of PI3, SPRR1B, LCN2 (lipocalin 2), MMP1, MMP9, MMP10, MMP12, SPP1, GJB2, Bcl-xl (BCL2L1), cIAP2 (BIRC3), S100A7A (koebnerisin), S100A9, SERPINB3, CEACAM6, KRT6B and SERPINB4 revealed that the expression levels of these proteins were higher in cholesteatoma than in external canal skin." (PMID 23285167, 2012).
chordoma (1 paper, 2024). Chordomas are rare malignant tumors arising from embryonic remnants of the notochord in axial skeleton. "When Brachyury genes are highly expressed in human chordoma cells, matrix metalloproteinases (e.g. MMP12, MMP13 and MMP24; 74) are also upregulated at the same time (which is also seen in hypochordal cells)." (PMID 39191278, 2024).
coeliac disease (1 paper, 2008). "While up-regulation of Wnt7A expression may provide a differentiation signal to epithelial cells, signalling via Wnt7a has also been shown to induce transcription of matrix metallproteinase 12 (MMP-12), an enzyme that has been implicated in coeliac disease pathophysiology." (PMID 18691394, 2008).
colonic diverticulosis (1 paper, 2023). "Given this intricate relationship between MMPs and colonic diverticulosis, this pilot study sought to investigate whether selected genetic variants in MMP3, MMP9, and MMP12 are associated with the incidence of colonic diverticulosis." (PMID 38004080, 2023).
cutis laxa (1 paper, 2016). Cutis laxa (CL) is an inherited or acquired connective tissue disorder characterized by wrinkled, redundant and sagging inelastic skin associated with skeletal and developmental anomalies and, in some cases, with severe systemic involvement. "Levels of dermal expression of MMP-3, MMP-9, and MMP-12 are increased in cutis laxa lesional fibroblasts or lymphocytes and are correlated with the degree of disruption of elastic fibers." (PMID 28116317, 2016).
cystic fibrosis (1 paper, 2018). Autosomal recessive disorder caused by pathogenic variants in the CFTR gene (cystic fibrosis transmembrane conductance regulator), which encodes a chloride and bicarbonate channel expressed in epithelial cells, and follow the diagnosis criteria. "ELANE which encodes neutrophil elastase, together with matrix metalloproteinase 12 (MMP12), has been reported in the development cystic fibrosis in lungs." (PMID 30245726, 2018).
demyelinating disease (1 paper, 2019). A broad group of disorders that affect the myelin sheaths that cover the neurons. "MMP12 is upregulated in MS and its animal model TME, indicating a possible key role of this molecule in the pathogenesis of demyelinating diseases." (PMID 30959793, 2019).
dermatophytosis (1 paper, 2025). A common fungal infection of the stratum corneum of the skin, hair, or nails by a dermatophyte. "Mmp12 and Sub7 were selected because they are considered virulence factors, given their ability to degrade keratin, which is of relevance in the pathogenesis of dermatophytosis." (PMID 40558967, 2025).
diverticulosis (1 paper, 2023). "Private haplotypes in individuals with diverticulosis included MMP3 −1715 5A/5A|MMP9 −1562 C/T|MMP12 −82 G/G (2%) and MMP3 −1715 6A/6A|MMP9 −1562 C/T|MMP12 −82 A/G (2%)." (PMID 38004080, 2023). "Among patients with diverticulosis, the most prevalent haplotypes included MMP3 −1715 5A/5A|MMP9 −1562 C/C|MMP12 −82 A/A (31%) and MMP3 −1715 5A/6A|MMP9 −1562 C/T|MMP12 −82 A/G (14%)." (PMID 38004080, 2023).
encephalitis (1 paper, 2019). An acute inflammatory process affecting the brain parenchyma. "In addition, patients with encephalitis had pronounced increased levels of MMP-3, MMP-8, and MMP-12 in their CSF compared to controls, suggesting an association to the severity of this manifestation." (PMID 30777092, 2019). "The patients with encephalitis had the most significantly increased levels of MMPs in CSF, and MMP-3, MMP-8, and MMP-12 were exclusively increased in this group, whereas MMP-9 in CSF was increased in the patients with VZV meningitis." (PMID 30777092, 2019).
endotoxemia (1 paper, 2015). "The effects of inhibition of MMP-12 on endotoxemia and inflammation-induced blood-cerebrospinal fluid barrier (BCSFB) disruption were assessed both in vitro and in vivo." (PMID 26351407, 2015). "Both in vivo and in vitro studies on the effects of the target compound on endotoxemia and BCSFB integrity clearly indicate a role for MMP-12 in these inflammatory processes and establish the use of this compound in a biological context." (PMID 26351407, 2015).
eosinophilia (1 paper, 2021). "The expression of MMP-12 was required for airway eosinophilia in OVA-induced allergic murine model." (PMID 34618857, 2021).
gastric tumors (1 paper, 2010). "Gene ontology analysis of gene expression in the gastric tumors indicates that PPARδ, MMP12, MMP13, Cxcl1, Cxcl5, S100A8, and S100A9 share both common and disparate pathway interactions that likely contributed to the tumorigenic phenotype." (PMID 21318167, 2010).
Gaucher disease (1 paper, 2011). Gaucher disease (GD) is a lysosomal storage disorder encompassing three main forms (types 1, 2 and 3), a fetal form and a variant with cardiac involvement (Gaucher disease - ophthalmoplegia - cardiovascular calcification or Gaucher-like disease). "The extremely high level of MMP12 expression (37 to 56-fold in 9 V/null lung and 16 to 22-fold in 9 V/null liver) implicates the aamφ in Gaucher disease progression." (PMID 21223590, 2011).
germinoma (1 paper, 2010). A malignant germ cell tumor arising in the central nervous system. "In the germinoma group (GPG), the presence of MMP-12, which is involved in promoting tumor metastasis, needs to be noted (labeled by a asterisk)." (PMID 20178649, 2010).
glomerulosclerosis (1 paper, 2024). A hardening of the kidney glomerulus caused by scarring of the blood vessels. "MMP-12, produced by macrophages infiltrating the glomeruli, contributes to the degradation of type IV collagen and fibronectin, and MMP-12 deficiency results in reduced glomerulosclerosis and fibrosis." (PMID 38674390, 2024).
heart failure (1 paper, 2021). Inability of the heart to pump blood at an adequate rate to meet tissue metabolic requirements. "From the same study, it was recently reported that 9 proteins (GDF-15, TIM-1, TRAIL-R2, SPON1, MMP-12, follistatin [FS], soluble urokinase-type plasminogen activator surface receptor [sU-PAR], OPG, and sST2) were associated with the development of heart failure." (PMID 33439866, 2021).
hemorrhage (1 paper, 2024). Loss of blood from the vascular compartment to the exterior or into nonvascular body space as a result of rupture or severance of the blood vessels. "In acute lobar ICH patients, MMP-12 plasma levels correlated with larger hemorrhage volume (p = 0.040) and irregular ICH shape (p = 0.036)." (PMID 39069622, 2024). "Also, we found a significant association between MMP-12 plasma levels and a more irregular shape of ICH, which is a neuroimaging parameter associated with hemorrhage expansion." (PMID 39069622, 2024).
hemorrhagic stroke (1 paper, 2022). A stroke caused by a bleed on the brain. "The pathologic role of MMP-12 has been demonstrated in a variety of neurologic diseases, including hemorrhagic stroke, spinal cord injury (SCI), and other pathologies." (PMID 36267234, 2022).
Hydrocephalus (1 paper, 2022). Hydrocephalus is an active distension of the ventricular system of the brain resulting from inadequate passage of CSF from its point of production within the cerebral ventricles to its point of absorption into the systemic circulation. "PRG2, MMP12, and COX4I1 are related to neurological function, and previous studies proved that MMPs were biomakers of BM; however, these proteins were not significantly differed between the hydrocephalus group and healthy groups in our study." (PMID 36052359, 2022).
hypercoagulability (1 paper, 2024). "Although the precise relationship between MMP-12 levels and VTE is not fully understood, with ongoing research, blood stasis, endothelial damage, and hypercoagulability are recognized as the three primary components of thrombosis." (PMID 38697862, 2024).
Idiopathic Pneumonia Syndrome (1 paper, 2014). "Likewise, MMP-12 deficient mice were not protected from the development of IPS (Idiopathic Pneumonia Syndrome) after bone marrow transplant, and in addition developed fibrosis associated with increased expression of integrin-β6, a potent activator of transforming growth factor (TGF)-β." (PMID 25302498, 2014).